INS (insulin)
Diseases named in the same sentence as INS in open-access papers (continued):
Sharing a sentence is not in itself a finding about the gene and the disease.
Insulin resistance (continued). "Skeletal muscle is the major site for insulin-stimulated glucose disposal, and muscle insulin resistance confers many negative health outcomes." (PMID 29057943, 2017). "In an animal NAFLD model, even without changes in weight and muscle insulin resistance, the ability of insulin to suppress hepatic glucose production was diminished." (PMID 29051770, 2017). "Insulin resistance is the biological condition where normal or elevated levels of insulin do not show the expected response in the blood glucose level or in other words the reduction in sensitivity of an organism's cells to insulin levels." (PMID 29057258, 2017). "Although LECT2 levels were not different between the presence and absence of insulin resistance, fasting insulin level (r = 0.24, P = 0.004) and HOMA-IR (r = 0.22, P = 0.010) were significantly correlated with LECT2 levels." (PMID 28278265, 2017). "One being GDM in an obese women, with pre-existing insulin resistance and a sufficient capacity to produce insulin in a non-pregnant situation, but decreased capacity to compensate for the added insulin resistance caused by pregnancy." (PMID 28253366, 2017). "Although insulin resistance was not improved, the supplementation with ZnCl2 increased insulin secretion in islets incubated with 16.7 mM glucose." (PMID 29053582, 2017). "Our findings suggest that these antiobesity, anti-insulin resistance effects of SYE could be mediated by the suppression of adipose tissue inflammatory cytokines and enhancing the insulin signaling pathway." (PMID 29085434, 2017). "Most importantly, osteoblasts in mice with DIO exhibit characteristics of insulin resistance as they do not respond to the stimulatory effect of insulin on the phosphorylation of IRS1/2." (PMID 28434032, 2017). "We did not have fasting specimens or measure HbA1c,28, 29 but our results for nonfasting insulin and glucose suggest an additional role for insulin resistance." (PMID 28923990, 2017). "Current antidiabetic treatments, especially the insulin-sensitizing class of drugs called thiazolidinediones (TZD) (i.e., rosiglitazone (Ros) and pioglitazone (Pio)), improve insulin resistance and glycemic control with benefit of improvement in rental complication." (PMID 29056962, 2017). "SGLT2 inhibitors are antidiabetic agents that are irrespective of the patient’s insulin secretory capacity or insulin resistance and are clearly different from those of existing drugs." (PMID 28391776, 2017). "Indeed, IL-1β induces insulin resistance by decreasing IRS-1 protein and inhibiting insulin-induced PKB phosphorylation." (PMID 28765650, 2017). "Whole body CYP2E1 knockout protected mice from HFD-induced obesity and insulin resistance, and it especially improved insulin sensitivity in hepatic and adipose tissues but not skeletal muscle tissue." (PMID 29081894, 2017). "Additionally, MAE improves hepatic insulin resistance through inhibiting PGC-1α and FOXO1 transcriptional activity to decrease gluconeogenesis as well as suppressing JNK phosphorylation to enhance insulin signalling transduction." (PMID 28713491, 2017). "According to another report, hyperinsulinemia and insulin resistance in the context of both dietary and genetic obesity improved in FABP4 deficient mice, but the effect of FABP4 on insulin sensitivity was not seen in lean mice." (PMID 28654680, 2017). "Nevertheless, in general, insulin resistance is induced by excess weight, physical inactivity, and a pathological condition in which cells do not respond properly to insulin." (PMID 29267310, 2017). "In this regard, we found that male rats displayed an increase in insulin resistance markers (HOMA-IR index and leptin/adiponectin ratio) and of liver TG content with aging, along with an important drop in mRNA levels of insulin and leptin receptors in liver and WAT." (PMID 28744221, 2017).
Insulin resistance (continued). "High insulin concentration in insulin resistance stimulates lipogenesis through the activation of sterol regulatory element-binding protein 1 (SREBP-1c), which inhibits insulin receptor substrate 2 (IRS-2) mediated insulin signaling." (PMID 29085434, 2017). "In conclusion, GRMD animals have changes in carbohydrate metabolism, with lower basal insulin and higher glucose in plasma compared with carriers and control animals, but do not show insulin resistance." (PMID 29209496, 2017). "However, glucose intolerance, and impaired insulin resistance with administration of Rapamycin (m-TOR inhibitor) has been reported, whereas sirolimus (Rapamycin) has also been reported to increase insulin mediated glucose uptake." (PMID 29371918, 2017). "Also, fat and lean body mass were negatively correlated with muscle insulin sensitivity indices, such as the Matsuda index and QUICKI, and positively correlated with hepatic insulin resistance indices, such as HOMA-IR and H-IR." (PMID 28721400, 2017). "While there are a small number of studies exploring the role of GH signaling on insulin resistance in patients with acromegaly, there are no published studies examining the effects of GH antagonism in insulin resistant, non-acromegalic patients." (PMID 28713554, 2017). "To investigate whether HFD-induced hepatic insulin resistance might be prevented by TM5441, we measured proteins involved in insulin signaling, such as Akt, GSK-3β, and JNK." (PMID 29163785, 2017). "Fourth, although HOMA models are widely used to assess insulin resistance and beta-cell function because they require only fasting glucose and insulin levels, HOMA-IR is less accurate for assessing insulin resistance than euglycemic hyperinsulinemic clamp method." (PMID 28575103, 2017). "VAT showed a stronger positive correlation than BF with blood pressure, triglycerides, LDL-cholesterol, glucose, insulin, and homeostasis model assessment-insulin resistance index and a stronger negative correlation with HDL-cholesterol." (PMID 28683146, 2017). "However, both fasting glucose and insulin levels were significantly increased after a 12‐week HFD, suggesting the development of insulin resistance between 4 to 12 week on a HFD." (PMID 28408640, 2017). "Since PTPN1 and STAT5A were demonstrated to impair insulin signaling, MCAT and its network may be novel mechanisms as to the offspring insulin resistance affected by intrauterine hyperglycemia." (PMID 29088862, 2017). "Alternatively, the definition of insulin resistance, which was assessed by the HOMA-IR and serum fasting insulin levels in our study, may be related to the results of the current study." (PMID 28704413, 2017). "Correspondingly, PA induced LTB4 production with increased ER stress and oxidative stress and impaired insulin signaling, suggesting that LTB4 may act in an autocrine fashion to induce skeletal insulin resistance." (PMID 28694473, 2017). "However, deletion of both insulin and leptin receptors from POMC neurons deteriorates glucose homeostasis and specifically leads to systemic insulin resistance and impaired fertility in mice." (PMID 28592656, 2017). "This change resulted in a higher degree of insulin resistance (p = 0.002, two-way ANOVA) and lower insulin sensitivity (p = 0.042, two-way ANOVA), measured as the HOMA-IR and R-QUICKI indexes, respectively, in both STD-GSPE and CAF-GSPE animals than in their counterparts." (PMID 28974704, 2017). "However, fasting insulin, HOMA-IR and triglycerides were significantly higher in overweight and obese participants, suggesting the presence of insulin resistance." (PMID 28129354, 2017). "Because of the compensatory hypersecretion of insulin by intact β-cells, fasting glucose levels remain in the normal range during early-stage insulin resistance." (PMID 29258604, 2017).
Insulin resistance (continued). "Moreover, higher plasma levels of insulin were found in HFD mice (4.42 ± 0.13 ng mL−1 vs. 2.93 ± 0.08 ng mL−1), in accordance with their peripheral insulin resistance." (PMID 29222408, 2017). "While we cannot correlate ZAG to insulin levels in our study, it is possible that the reduction in ZAG following RYGB may result in decreased insulin resistance and investigating this relationship would be an area for future research." (PMID 29367881, 2017). "Insulin modulates D-glucose homeostasis, and a reduced response or a lack of response to this hormone (hereafter referred as “insulin resistance”) is characteristic in several pathologies, including diabetes mellitus and obesity." (PMID 29104874, 2017). "in type 2 DM the body does not use insulin properly leading to higher level of fasting blood glucose, increased plasma insulin level, impaired glycemic control (higher HbA1c) and insulin resistance (IR)." (PMID 28811774, 2017). "When grouped by insulin resistance, the groups differed significantly in insulin and leptin, but not glucose or triglycerides." (PMID 28093279, 2017). "Insulin resistance is complex, so it should not be surprising that the extent of fiber type-related insulin resistance is not uniform across all insulin resistant conditions." (PMID 29057943, 2017). "An insulin tolerance test showed insulin resistance, although the glucose tolerance was not different from control mice." (PMID 29107299, 2017). "Concentration of glucose and insulin did not change after the study period, and also, regular intake of orange juice did not induce significant changes on marker of insulin resistance (HOMA-IR) in the investigated sample." (PMID 28469541, 2017). "Insulin resistance is the most important feature of T2DM, which is characterized by reducing sensitivity or responsiveness of muscle, liver, and adipose tissue to the metabolic actions of insulin." (PMID 29362600, 2017). "Furthermore, the ITT showed that while aged AAV-GFP mice developed insulin resistance compared to younger AAV-GFP mice, as evidenced by slower systemic glucose clearance, aged AAV-ΔFosB mice maintained higher insulin sensitivity." (PMID 28121620, 2017). "Thiazolidinediones (TZDs) are peroxisome proliferator-activated receptor gamma (PPARγ) agonists that lower insulin resistance without directly affecting insulin secretion." (PMID 29379799, 2017). "Although current evidence for the role of SAA in insulin signaling is contradictory, SAA levels have been correlated with insulin resistance and T2DM, which may be related to the pro-inflammatory properties of SAA." (PMID 28686216, 2017). "Indeed, incubation of cardiomyocytes with HG resulted in insulin resistance within 24 h, whereas NOX2 inhibition restored insulin signalling." (PMID 28128227, 2017). "The central key features of T2DM are a defect in insulin resistance and/or insulin secretion, which lead to hyperglycaemia and disrupt the normal relationship between insulin sensitivity and pancreatic β-cell function." (PMID 29098166, 2017). "The insulin in HFD-fed mice was significantly higher than that of the mice fed with normal chow, indicating that high fat diet could induce hyperinsulinemia and insulin resistance." (PMID 28452943, 2017). "Although, plasma insulin levels decrease to a certain amount by increasing extracellular IDE, it is the level of cytosolic IDE synthesis, not extracellular levels, that is important for the treatment of insulin resistance in diabetic subjects." (PMID 28070499, 2017). "Type 2 diabetes or non-insulin-dependent DM is a common form of insulin resistance that maintains glucose homeostasis by increasing the release of insulin." (PMID 28758131, 2017). "With continuing insulin resistance, a compensatory increase in insulin production maintains normal circulating glucose concentrations." (PMID 29075006, 2017).
Insulin resistance (continued). "However, ISI is greatly affected by the insulin secretion ability, and if the insulin secretion ability is decreased, ISI shows low insulin resistance." (PMID 28695132, 2017). "Type 2 diabetes is known to develop as a consequence on insulin secretion not compensating for insulin resistance; however, the precise mechanism by which the impairment of the compensation leads to type 2 diabetes is unclear." (PMID 29104217, 2017). "Interestingly, we found that 3-month-old HSLAKO mice had lower levels of insulin than controls, but 8-month-old HSLAKO mice had higher levels, suggesting an age-related development of insulin resistance." (PMID 29232702, 2017). "Increased expression of these intermediates of cytokine signaling induces insulin resistance via the alteration of IR activation and expression, as well as by increasing the phosphorylation of the IRS-1 in serine residues, which impairs insulin signal transduction." (PMID 28677618, 2017). "Insulin resistance in the liver is selective in that insulin fails to suppress gluconeogenesis but continues to boost fatty acid synthesis." (PMID 28848738, 2017). "Gestational diabetes mellitus (GDM) is characterized by insulin resistance accompanied by low/absent beta-cell compensatory adaptation to the increased insulin demand." (PMID 29312141, 2017). "Additionally, to confirm the status of peripheral insulin resistance, mice fed a LFD and HFD were injected with insulin and, 8 min." (PMID 28244645, 2017). "As expected, homeostasis model assessment of insulin resistance (HOMA-IR), the area under the curve for glucose (AUCglucose) and insulin (AUCinsulin) were significantly increased, while M-value was significantly decreased in PCOS women with IR compared with the controls." (PMID 29228555, 2017). "Moreover, the insulin sensitivity calculated by HOMA-IR, allowed us to conclude that high fat feeding results in insulin resistance." (PMID 28184199, 2017). "Once the excessive secretion of insulin can no longer compensate for the degree of insulin resistance, clinically significant hyperglycemia will happen." (PMID 28881687, 2017). "In addition to preventing fibrosis, it improved liver function and decreased serum levels of glucose, insulin concentrations and HOMA-IR, indicating a significant decrease in insulin resistance." (PMID 28718838, 2017). "To determine whether administration of A. actinomycetemcomitans induced impaired glucose tolerance and insulin resistance, we performed a glucose tolerance test (GTT) and an insulin tolerance test (ITT) on both dietary groups at 6 weeks." (PMID 29066788, 2017). "Severe insulin resistance can develop independent of obesity as a consequence of monogenic gene defects impacting on insulin signalling or adipose tissue development." (PMID 28566439, 2017). "We found that adipose tissue-specificglucose uptake rates were not affected by GC-induced whole body insulin resistance,supporting an adipose tissue-specific insulin-sensitizing GC effect." (PMID 28323916, 2017). "Insulin secretion continues to decrease during deterioration of glucose tolerance in progressors; insulin secretion continues to increase in non-progressors who keep NGT despite increased insulin resistance." (PMID 28878826, 2017). "In our study the mechanism behind the raised blood pressure did not appear to involve altered insulin sensitivity, despite the established link between insulin resistance and hypertensive syndromes of pregnancy." (PMID 29153680, 2017). "For example, many mechanisms have been postulated as the root of insulin resistance, and it is likely that no one pathway is responsible for the dysfunction of insulin signalling." (PMID 26227946, 2016). "The common denominator behind the metabolic syndrome is insulin resistance, that is, a lack of sensitivity of peripheral organs to insulin, which has emerged as the root mechanism explaining the occurrence of these disorders." (PMID 26794239, 2016).
Insulin resistance (continued). "Recently, it was reported that the certain miRNAs targeting the 3’UTR of the insulin signaling intermediates’ mRNA are modulated by the SFA-induced obesity and NAFLD, and that these miRNAs participate actively in the development of hepatic insulin resistance." (PMID 28036389, 2016). "Although LIrs1/2DKO mice showed severe insulin resistance and hyperglycaemia on a HF diet, as observed in obese insulin-resistant mice in general, these mice failed to develop steatosis in this study." (PMID 27708333, 2016). "NR4A1 has been shown to be induced by insulin and thiazolidinedione drugs in 3T3-L1 adipocytes, and NR4A1 gene expression is enhanced in skeletal muscles and adipose tissues in multiple rodent models of insulin resistance." (PMID 27322146, 2016). "While the etiology of insulin resistance in “Double Diabetes” remains to be determined, it is clear that it does not parallel other insulin resistant states (i.e. T2D or obesity), as patients with T1D often do not display associated factors such as obesity." (PMID 27197730, 2016). "Because the insulin and glucose levels changed only marginally, we conclude that insulin resistance does not contribute to the steatosis in SLC-KO mice at least during the first five weeks after doxycycline administration." (PMID 27185526, 2016). "However, HFD-induced insulin resistance, augmentation in TyG and HOMA indexes, and the increase in plasma insulin concentration were only observed in aged animals." (PMID 27057272, 2016). "Adult Fxyd2−∕− mice also exhibited a mild pancreatic phenotype with enhanced glucose tolerance, elevation of circulating insulin, but no insulin resistance." (PMID 27014088, 2016). "Other studies have assessed insulin resistance by measuring the homeostatic model assessment index of insulin resistance (HOMAIR) or levels of C-peptide, which has a longer half-life than insulin and is considered a valid biomarker of pancreatic insulin secretion." (PMID 27046222, 2016). "When administered at a controlled concentration, insulin is also ineffective at suppressing circulating FFA levels in vivo in fasted RictorAdipoq-cre mice, which is consistent with insulin resistance but could reflect liver dysfunction." (PMID 27098609, 2016). "In agreement with the previous reports, high-fat feeding in both male and female mice impaired insulin sensitivity (assessed as HOMA-IR) as compared to their STD-fed counterparts; however, the variations among individual mice regarding the degree of insulin resistance were substantial." (PMID 27183228, 2016). "In 1990, in a study made in obese and lean subjects determined a correlation between insulin resistance (hyperglycaemia and hyperinsulinemia), and lack of vasodilatory effects of insulin in leg blood flow (LBF)." (PMID 27014078, 2016). "Other studies also showed that AN was associated with hyperinsulinemia, which indicated that AN patients had reduced insulin sensitivity and increased insulin resistance even worse than obese patients without AN." (PMID 27190511, 2016). "The fact that insulin-stimulated IR phosphorylation and AKT signalling is largely intact in the mutant WATs yet insulin fails to efficiently stimulate glucose uptake indicates that RictorAdipoq-cre mice have selective adipose tissue insulin resistance." (PMID 27098609, 2016). "One limitation is that HOMA-IR calculated with fasting glucose and fasting insulin levels rather than hyperinsulinemic euglycemic clamp, which remains the “gold standard” for accurately determining insulin resistance, were used in the present study." (PMID 27473122, 2016). "Considering the key role played by insulin-resistance and androgen excess in PCOS patients, the insulin-sensitizing effects of both MI and DCI were tested in order to ameliorate symptoms and signs of this syndrome, including the possibility to restore patients' fertility." (PMID 27579037, 2016).